CXCL5 (C-X-C motif chemokine ligand 5)
Diseases named in the same sentence as CXCL5 in open-access papers (continued):
Sharing a sentence is not in itself a finding about the gene and the disease.
bacterial infections (15 papers, 2010 to 2025). "Thus, LIX/CXCL5-targeting therapeutics may restrict pathogenic neutrophil infiltration in the lung and may alleviate lung injury during secondary bacterial infections." (PMID 36475755, 2023). "In bacterial infections, a CARD9 deficiency results in a decrease in inflammatory cytokines (IL-1β, IL-6, and TNF-α) and chemokines (CXCL1, CXCL2, and CXCL5)." (PMID 38473845, 2024). "One chemokine CXCL5, plays a scavenging role to regulate pulmonary host defense against bacterial infection, but its role in pulmonary influenza virus infection is underdetermined." (PMID 34868067, 2021). "Whereas LPS, widely used to mimic bacterial infections in vitro, evoked distinct pro-inflammatory responses in HBMEC, expressed by mRNA and protein increases for CXCL5, IL-1α, IL-1β, IL-6, IL-8, MCP-1, MCP-3, and TNF-α, Ureaplasma spp." (PMID 31336668, 2019). "This is in agreement with higher expression of CXCL5, IL1B, IL8 and TNF described for several bacterial infections, indicating that the immune system is activated to eliminate bacteria." (PMID 21176181, 2010). "Viral and bacterial infections increase expression of TNF-α, IL-1β, and other cytokines that stimulate NF-kB activation responsible for amplifying and driving expression of downstream cytokines/chemokines such as CXCL5." (PMID 40494897, 2025).
inflammation (9 papers, 2011 to 2025). Aberrant reaction of the microcirculation characterized by movement of fluid and leukocytes from the blood into extravascular tissues. "Pulmonary inflammation was also assessed by quantifying Il-6, Tnf, Cxcl2 and Cxcl5 mRNA expression levels in lung tissue." (PMID 34717665, 2021). "Consistent with this expression pattern, treatment with anti-CXCL5 antibody attenuates lung neutrophil accumulation in rodent models of lung inflammation." (PMID 28486498, 2017). "Produced by resident lung cells (such as pulmonary epithelial cells and platelets during lung inflammation), Cxcl5 plays a key role in controlling chemokine clearance and can negatively regulate neutrophil influx into the lungs by affecting the concentration of other chemokines in the bloodstream." (PMID 39493864, 2024). "Systemic and pulmonary inflammation was measured by enzyme-linked immunosorbent assays of plasma and bronchoalveolar lavage (BAL), respectively, which included tumor necrosis factor alpha (TNF-α), interleukin 6 (IL-6), IL-10, C-X-C motif ligand 2 (CXCL2), and CXCL5." (PMID 38928327, 2024). "CXCL5 is a chemoattractant chemokine from CXC family that activates neutrophils and also plays a role in neutrophil trafficking during lung inflammation induced by LPS." (PMID 30616505, 2019).
cardiovascular disease (4 papers, 2009 to 2025). "We hypothesized that polymorphisms in the CXCL5 gene, which encodes the neutrophilic chemokine ENA-78, are associated with blood pressure in cardiovascular disease (CVD)-free adults and that these polymorphisms are functional." (PMID 23245743, 2012).
metabolic disease (4 papers, 2017 to 2024). A congenital disorder (due to inherited enzyme abnormality) or acquired (due to failure of a metabolically important organ) disorder resulting from an abnormal metabolic process. "However, as shown in this study, the involvement of CXCL5 in metabolic diseases has also been reported." (PMID 34537202, 2021).
kidney diseases (3 papers, 2024 to 2025). "Consistent with previous findings, we have confirmed upregulation of several inflammatory mediators, including those modulated by NLRP2, namely Il6, Cxcl1 and Cxcl5 at early and late stages of the kidney disease." (PMID 38633264, 2024).
retinopathy (1 paper, 2009). "Participation of CXCL5 in thedevelopment of retinopathy was suggested by the increased levels of thischemokine found in retinopathy diabetic patients." (PMID 20157549, 2009).
vasculopathy (1 paper, 2021). "Of note, the various CXC chemokines, such as CXCL4 (ELR-), CXCL5 (ELR+), CXCL6 (ELR+), CXCL12 (ELR−), CXCL13 (ELR−), and CXCL14 (ELR−), are thought to be associated with the development of SSc vasculopathy." (PMID 34774095, 2021).
CXCL5 also shares sentences with these, for which no sentence is quoted: endometrial cancer (4 papers); Anxiety (3); idiopathic pulmonary fibrosis (3); lymph node (3); multiple myeloma (3); schizophrenia (3); atopic dermatitis (2); leukemia (2); lymphoma (2); pemphigus vulgaris (2); Pleural effusion (2); psychiatric disorder (2); thrombosis (2); type 1 diabetes (2); acquired metabolic disease (1); adenocarcinoma (1); Adrenocortical carcinoma (1); age-related macular degeneration (1); allergic asthma (1); amoebiasis (1); aneurysm (1); ankylosing spondylitis (1); aortic valve disease (1); aplastic anemia (1); astrocytoma (1); autism (1); autoimmune polyendocrine syndrome type 1 (1); bacterial pneumonia (1); benign prostatic hyperplasia (1); bordetella pertussis infection (1).
A further 95 diseases each share a sentence with CXCL5 in 1 paper.